EZH2 (enhancer of zeste 2 polycomb repressive complex 2 subunit)
Diseases named in the same sentence as EZH2 in open-access papers (continued):
Sharing a sentence is not in itself a finding about the gene and the disease.
tumor (continued). "However, it should be noted that the effectiveness of sunitinib is impeded by elevated levels of myeloid-derived suppressor cells (MDSCs) within the tumor microenvironment, which are induced by both tumor burden and the administration of EZH2 inhibitors." (PMID 38600608, 2024). "This process is mediated in part by EZH2 and targets genes related to the tumour microenvironment." (PMID 39739419, 2024). "The EZH2-NF-κB axis not only enhances the proliferation and survival of cancer cells but also increases their invasive potential, making it a significant driver of tumor growth and dissemination." (PMID 39120328, 2024). "In summary, our study revealed the prognostic value of EZH2 in skull base chordoma and found that EZH2 is correlated with tumor stemness and M2 macrophage infiltration, providing a theoretical basis for the application of EZH2 inhibitors in skull base chordoma." (PMID 38882008, 2024). "The aim of this study was to determine whether the tumor marker EZH2 can be used to evaluate the potential aggressiveness of high-risk localizations of cSCC and to analyze various evaluation methods for its expression." (PMID 40135141, 2024). "In summary, these studies highlighted the link between EZH2, Myc, and tumor progression." (PMID 38534385, 2024). "A further potential focus for future studies could therefore be to determinate further correlations of EZH2-expression during cell invasion and even an analysis between primary tumor and LNM." (PMID 40135141, 2024). "Further studies addressing the functional significance of altered EZH2/pERK expression in tumor progression would be necessary to strengthen this hypothesis." (PMID 38339397, 2024). "Hence, EZH2 is involved in a wide range of tumor processes [including tumorigenesis, cell cycle progression, metastasis, cancer immunity, and apoptosis] and is a promising therapeutic target." (PMID 38225241, 2024). "Treatment with GSK343 at higher doses significantly decreased the presence of large and prominent cell nuclei, and dysplasia in tongue tissue compared to the OSCC group, reestablishing tissue architecture and counteracting tumor progression through EZH2 inhibition." (PMID 39204206, 2024). "In fact, EZH2 inhibition potentiated tumor progression in immunodeficient mice." (PMID 39403928, 2024). "Previous data indicate that EZH2 behavior could be influenced by tumor topography and its histological characteristics." (PMID 40135141, 2024). "However, the antitumor effects of siRNA in a mouse xenograft tumor model demonstrated that ITGA11 siRNA treatment outperformed EZH2 siRNA treatment, indicating the superior efficacy of ITGA11 siRNA in suppressing tumor growth." (PMID 38664825, 2024). "Targeting MICU1 can compensate for the role of EZH2 in regulating tumor cell apoptosis." (PMID 38600608, 2024). "EZH2 inhibition could potentially be used to increase tumor immunogenicity and/or improve responses to immunotherapies." (PMID 39403928, 2024). "Available data have supported EZH2 involved in metastatic spread and tumor angiogenesis." (PMID 36959801, 2023). "Interestingly, we demonstrated that PAR5 exerts its tumor suppressor role by inhibiting the activity of EZH2 on E-cadherin gene expression." (PMID 37238229, 2023). "In summary, EZH2 was abnormally overexpressed in multiple human cancer tissues, indicating that it may function as an oncogene in various tumor development and progression." (PMID 36545914, 2023). "The expression levels of EZH2 in tumor tissues were also assessed through the HPA website." (PMID 36545914, 2023). "This evidence suggests that UXT interacts with EZH2 in tumor cells." (PMID 37152054, 2023). "Tumor-infiltrating EZH2+ T cells are polyfunctional effectors resistant to apoptosis." (PMID 37565053, 2023).
tumor (continued). "Several recent studies not only linked this role of EZH2 to HCC development but also bridged its pro-oncogenic function to the decrease of PD-L1 and shaping of tumor immunosuppressive microenvironment, suggesting that HCC patients with EZH2 mutations should be treated with immunotherapy carefully." (PMID 36959801, 2023). "Generally, EZH2, as a classic oncogene inhibitor, is characterized by a direct anti-tumor effect." (PMID 37239949, 2023). "EZH2 is essential for cell proliferation in tumor cell lines." (PMID 37445833, 2023). "Finally, to test the efficacy of this combination therapy in vivo, we assessed combined treatment of EPZ-6438 and the orally available VTP5046958 on tumor growth using the EZH2 mutant SuDHL10 xenograft model." (PMID 37460547, 2023). "In this case, tazemetostat inhibits EZH2 and stops the growth of tumor cells." (PMID 37228649, 2023). "Multiple findings have exhibited that BMSC‐derived exosomes carrying miRNAs could suppress EZH2 expression to inhibit the tumour cell proliferation, migration and invasion, and induce its apoptosis, thereby restraining the development of tumours." (PMID 37698037, 2023). "EZH2 staining of lymphocytes may be useful as an internal positive control but must be carefully distinguished from tumor cell staining." (PMID 37190202, 2023). "Finally, it was shown that UPK1A-AS1 and EZH2 are overexpressed in HCC tissues compared to the adjacent non-tumor tissues and that their expression levels inversely correlate with patient prognosis." (PMID 37111734, 2023). "The results above show that CA could enhance the tumor-suppressive effect of EZH2 knockdown in mice models, suggesting that CA could be a potential therapeutic candidate in combination with EZH2 inhibitors." (PMID 38264522, 2023). "Having established FOXP2 as a direct target of PRC2 in lung epithelial cells, we sought to understand if FOXP2 could drive the phenotypic differences observed in Ezh2 null tumor cells." (PMID 36670102, 2023). "In short, EZH2 was mainly expressed in the nuclei of PC tumor cells." (PMID 37198697, 2023). "Combinatorial EZH2 knockdown and T/P treatment also had profound anti-tumor effects." (PMID 37142692, 2023). "Subsequent analysis revealed that EZH2 could promote tumor immune evasion through T-cell dysfunction and T-cell exclusion." (PMID 36545914, 2023). "Therefore, EZH2 has been raised as a potential target for tumor therapy, and both preclinical and clinical studies on EZH2 inhibitors are intensively pursued." (PMID 38146588, 2023). "Consequently, numerous EZH2 inhibitors have been developed and recognized as effective anti-tumor agents in cancers." (PMID 38264522, 2023). "Notably, the role of EZH2 is not limited to tumor and immune cells, but affects the entire tumor microenvironment." (PMID 37239949, 2023). "Similarly, Sasaki and Sudo also declared that EZH2 is highly expressed in cancer tissues and is closely related to the degree of tumor malignancy." (PMID 37689710, 2023). "In our in vivo model, EZH2 modulation using CRISPR/Ca9 greatly reduced tumor growth and Ki-67-positive cells and exhibited a significant reduction in the number of cancer-associated fibroblasts (CAFs) in tumors derived from SW1736-edited cells compared to control." (PMID 37175580, 2023). "Out of the 55 upregulated genes, a 5 gene-signature (CDK1, EZH2, CCNB1, CCNA2, and AURKA) involved in cell regeneration was positively correlated with the status of tumor hypoxia and clustered with stemness-associated genes, as recognized by Parametric Gene Set Enrichment Analysis (PGSEA)." (PMID 37189841, 2023). "Further, the knockout of EZH2 mimicked the tumor inhibition of miR-26a in UM cells." (PMID 36873948, 2023). "Conversely, inhibiting EZH2's activity can slow down tumour growth." (PMID 38041544, 2023). "EZH2i are in clinical trials for diverse malignancies and the striking EZH2 and Menin co-dependency suggests that sensitivity to EZH2i may predict tumours likely to also respond to MENi." (PMID 36635503, 2023).
tumor (continued). "Strikingly, Ezh2 null tumor cells had a significantly higher propensity to metastasize to areas including lymph nodes, pleural space, chest wall, diaphragm, and liver than Ezh2 WT or heterozygous tumor cells." (PMID 36670102, 2023). "Collectively, studying the regulation of EZH2 by different types of PTMs and their regulation in carcinogenesis, as well as elucidating its intrinsic molecular mechanism, will open up a potential and promising approach for tumor therapy." (PMID 36672374, 2023). "Besides recruitment, EZH2 affects anti-tumor immunity by modulating the differentiation and functional activation of the immune cells." (PMID 36900330, 2023). "Compared to the control group, the tumor volume and weight decreased in the EZH2 knockdown groups." (PMID 38008711, 2023). "Interestingly, the binding of EZH2, a well‐known tumor‐promoting protein, to was found to be highly likely." (PMID 37747077, 2023). "Importantly, miR-101 inhibits tumor proliferation and migration and triggers apoptosis by targeting EZH2, or by connecting to lncRNAs, resulting in dysregulation of each other’s expression." (PMID 38203269, 2023). "Therefore, we argue that a better understanding of the molecular mechanisms that sensitize cancer cells to EZH2 inhibition and modulate tumor microenvironment will likely provide important insights for new treatment options for MPM." (PMID 36900330, 2023). "However, both EZH2 and EZH2-ΔSET were able to rescue the suppressed tumor growth and tumor sphere formation induced by EZH2 silencing." (PMID 37210576, 2023). "In tumor cells, EZH2 inhibits the genes responsible for the suppression of tumor development." (PMID 37111734, 2023). "On the contrary, inhibition of EZH2 may impair Foxp3 expression, reduce the suppressive activity of Tregs, reshape the tumor microenvironment, enhance CD8 and CD4 effector T cell recruitment and function, and thus enhance antitumor immunity." (PMID 37909018, 2023). "These divergent results suggest that cancer cell intrinsic and TME signals may account for the distinct effects of EZH2 inhibitor in different tumor types." (PMID 36900330, 2023). "Several growth-suppressing genes, including p21, p16, and p27, and pro-death genes, including F-box protein 32 protein (FBOX32), are downstream targets of EZH2 and participate in proliferation, cell cycle arrest, senescence, and apoptosis of tumor cells, and ultimately determines the cell fate." (PMID 36672374, 2023). "Then, the expression levels of EZH2 in different normal and tumor tissues were investigated." (PMID 36545914, 2023). "Moreover, the expression levels of EZH2 were significantly increased in lung, liver, prostate, and kidney metastatic tissues compared with corresponding primary tumor tissues." (PMID 36545914, 2023). "This section focuses on the function of EZH2 on tumor immunity in HCC." (PMID 37268997, 2023). "Treg cells in tumor tissues specifically express high levels of EZH2, resulting in tumor tolerance." (PMID 36627707, 2023). "Rather, deletion of either Eed or Ezh2 accelerated tumor progression." (PMID 36635771, 2023). "It is worth noting that BAP1 and EZH2 are the only markers that are localized in the nuclei of tumor cells, whereases the IHC analysis of the other markers results in a cytoplasmic staining wherein variable intensity can challenge the detection of a positive signal from the background." (PMID 36900330, 2023). "By contrast, expression of EZH2 in cancer cells may dampen anti-tumor immunity and hinder the infiltration of the tumor by effector T cells through EZH2- and DNMT1-mediated epigenetic silencing of TH1-type chemokines (i.e., CXCL9 and CXCL10)." (PMID 36627707, 2023). "When EZH2 is abnormally activated, it leads to the suppression of tumour suppressor genes." (PMID 38041544, 2023).
tumor (continued). "To determine whether EZH2 suppression facilitated anti-tumor NK cell immunity through CCL2 induction, we also treated mice transplanted with shEzh2 KPC1 PDAC tumors with vehicle, T/P, and/ or a mAb targeting CCL2 (2H5)." (PMID 37142692, 2023). "Therefore, distinct SASP chemokines are important for NK and T cell migration into the PDAC TME and enable the immune-mediated anti-tumor effects observed upon EZH2 suppression." (PMID 37142692, 2023). "For instance, Tian and colleagues demonstrated that curcumol could downregulate HOTAIR expression, which induces the suppression of EZH2, leading to the inhibition of tumor growth." (PMID 37240232, 2023). "We, therefore, tested if combined inhibition of MEN1 (MI-503 or VTP50469) and EZH2 (EPZ-6438) could result in synergistic effects on tumor transcriptome and growth in vitro and in vivo." (PMID 37460547, 2023). "The expression of EZH2 was variable in adenocarcinoma, depending upon the grade of tumor." (PMID 37131568, 2023). "Additionally, treatment with the EZH2 inhibitor GSK126 resulted in the regression of ARID1A mutant tumours." (PMID 38041544, 2023). "EZH2-mediated epigenetic silencing of miRNAs also contributes to tumor progression." (PMID 38008711, 2023). "Interestingly, the authors demonstrated that miR-138 suppresses tumor progression by targeting the histone methyltransferase EZH2." (PMID 37369946, 2023). "EZH2 functions as a key factor promoting tumor growth and metastasis in many malignancy models." (PMID 35841331, 2023). "Accumulating studies suggest that EZH2 plays an important role in mediating immune escape by suppressing immune identification and activation, enhancing immunological checkpoints, and fostering an immunosuppressive tumor microenvironment." (PMID 36672677, 2023). "In addition, EZH2 inhibition enhanced NK cell anti-tumor effects and immune recovery when combined with the TIGIT-blocking monoclonal antibody." (PMID 37239949, 2023). "Moreover, the expression of SNHG4, TK1, AURKA, RRM2 and EZH2 in the tumor tissues was found to be significantly elevated after SNHG4 overexpression." (PMID 37596700, 2023). "Notably, Akt/NICD1+Ezh2 (A/N+E2) mice developed a large tumour load 4 weeks after plasmid injection, while Akt/NICD1/Vector (A/N+V) mice developed only a small number of small lesions in the liver." (PMID 38050190, 2023). "Cancer cells acquire enhanced Top2 functions to cope with the stress generated by transcription and DNA replication during rapid cell division since cancer driver genes such as Myc and EZH2 hijack Top2 in order to realize their oncogenic transcriptomes for cell growth and tumor progression." (PMID 36678591, 2023). "Indeed, EZH2-dependent epigenetic reprograming has emerged as a crucial modulator of tumor-infiltrating immune cells in different types of malignancies, but it has never been fully explored in MPM." (PMID 36900330, 2023). "EZH2-mediated H3K27me3 is thought to initiate tumorigenesis through a variety of mechanisms, which ultimately establish the silenced chromatin environment and prevent the expression of tumor suppressor genes." (PMID 37069142, 2023). "Depleting EZH2 in T cells results in poor anti-tumor immunity." (PMID 36627707, 2023). "As a popular epigenetic target, there is mounting evidence demonstrating that EZH2 can control a wide range of tumor-infiltrating lymphocytes, form an immunosuppressive microenvironment within the tumor, and allow tumor cells to escape the recognition and destruction of the immune system." (PMID 38008753, 2023). "Moreover, TOP2A is more highly expressed in EZH2-high tumor tissues than in EZH2-low tumor tissues and normal tissues, and the coordinated expression of EZH2 and TOP2A is associated with a worse prognosis in HCC." (PMID 38008711, 2023). "In addition to affecting tumor proliferation and metastasis, EZH2 is also involved in tumor immunity, including immune evasion, NK-cell-mediated cytotoxicity, and T-cell function." (PMID 37268997, 2023).
tumor (continued). "Moreover, ablation of ATF3 prevented tumor regression in response to EZH2 and HDAC inhibitors in vivo (light blue line)." (PMID 37104245, 2023). "Indeed, inhibition of EZH2 improves the response to anti-CTLA4 by regulating tumor cytotoxic effector T cells and changing the phenotype of Tregs into effector-like T cells." (PMID 37928272, 2023). "Although hnRNPK and EZH2 are overexpressed and exert oncogenic functions in several cancers, recent studies indicated that some lncRNAs could convert them into tumor-suppressors." (PMID 36768150, 2023). "Finally, these findings emphasize the importance of ERβ’s ability to repurpose EZH2 for tumor suppressive activities." (PMID 36926316, 2023). "However, it is uncertain how much EZH2 contributes to EMT-mediated immune escape, as EZH2 also controls tumor growth and metastasis." (PMID 36823234, 2023). "To test whether EZH2/PRC2 regulates FOXP2 expression through its enzymatic activity, we re-expressed EZH2 WT and enzymatic-incompetent F667I mutant EZH2 in the Ezh2 null mouse tumor cells." (PMID 36670102, 2023). "In addition to the classical PRC2‐mediated and H3k27me3‐dependent functions of EZH2 in malignant tumours, a part of the study found that EZH2 also has non‐classical functions in promoting tumour progression." (PMID 38050190, 2023). "Another critical event is that EZH2 suppresses tumor growth suppressor genes." (PMID 36672374, 2023). "In summary, our study revealed that the co-administration of FGFR4 inhibitor with EZH2 inhibitor could significantly inhibit tumor growth, which may be a potential option for the future clinical treatment of HCC." (PMID 37085881, 2023). "Destruction of EZH2 in neoplastic cells can lead to the inhibition of tumor growth." (PMID 37107631, 2023). "High levels of EZH2 often correlate with advanced tumor stage and poor prognosis, so inhibition of EZH2 may block proliferation and survival." (PMID 37446319, 2023). "Combining EZH2 inhibitior with ICB reduces tumor growth by changing the expression of B2M." (PMID 38041084, 2023). "Furthermore, we have observed a potent antitumoral effect of EZH2 inhibition, as evidenced by reduced cell count, migration and invasion in vitro, and inhibited tumor growth in a xenograft mouse model." (PMID 37175580, 2023). "We speculate that UXT may regulate tumor cell apoptosis or other processes by recruiting EZH2 or stabilizing EZH2 as a chaperone." (PMID 37152054, 2023). "EZH2 acts as a tumor suppressor in LUAD, MDS, AML, T-ALL, and PMF." (PMID 38036730, 2023). "EZH2, a member of the polycomb repressive complex 2, induces trimethylation of the downstream gene at the histone three lysine 27 (H3K27me3) position to inhibit tumor cell proliferation." (PMID 37239949, 2023). "Additionally, the study employed Taqman quantitative real-time RT-PCR to measure EZH2 expression in matched tumor and normal tissue samples." (PMID 37909018, 2023). "In summary, EZH2 might facilitate tumor immune evasion by decreasing T-cell infiltration, but also promote T-cell dysfunction, ultimately resulting in the short survival time of cancer patients." (PMID 36545914, 2023). "In tumor cells, down-regulation of miRNA was significantly correlated with EZH2 over-expression because of direct inhibition of the transcription and translation process of EZH2 by miRNA." (PMID 36672374, 2023). "To investigate whether FGFR4 and EZH2 inhibitors could synergistically repress tumor growth in vivo, we first administered Roblitinib and CPI-169 alone or in combination in the zebrafish HCC primary tumors." (PMID 37085881, 2023). "Indeed, we found that SMA+ myofibroblasts that are abundant in the PDAC TME contribute to NK as well as T cell immune suppression by promoting EZH2-mediated repression of pro-inflammatory SASP genes in tumor cells." (PMID 37142692, 2023).